PRAMENP (PRAME N-terminal like, pseudogene)
Synonyms: FLJ16327; formerly PRAMEL; PRAMEF24P
Gene: Transcribed unprocessed pseudogene on chromosome 22 (21,991,236 to 21,995,428, reverse strand). Ensembl gene ENSG00000197549.
Diseases named in the same sentence as PRAMENP in open-access papers:
PRAMENP is named in the same sentence as 1 disease in open-access papers, as found by Europe PMC text mining. Sharing a sentence is not in itself a finding about the gene and the disease.
PRAMENP shares sentences with these, for which no sentence is quoted: chronic lymphocytic leukemia (1 paper).